FFAR4 (free fatty acid receptor 4)
Diseases named in the same sentence as FFAR4 in open-access papers (continued):
Sharing a sentence is not in itself a finding about the gene and the disease.
metabolic disease (26 papers, 2014 to 2025). A congenital disorder (due to inherited enzyme abnormality) or acquired (due to failure of a metabolically important organ) disorder resulting from an abnormal metabolic process. "The free fatty acid receptor 4 (FFAR4) is a G protein-coupled receptor for endogenous medium- or long-chain fatty acids that attenuates metabolic diseases and inflammation." (PMID 39062812, 2024). "FFAR4 is targeted therapeutically in clinical trials for the treatment of metabolic disease (clinicaltrials.gov identifier: NCT03285750, NCT02444910, NCT03062592, NCT05068557)." (PMID 37108233, 2023). "In conclusion, our results indicated that the beneficial effects of endogenous n-3 PUFAs on metabolic disorders, which were mediated by Ffar4." (PMID 36771292, 2023). "Moreover, another important hypothesis is that the free fatty acid receptor 4 (FFAR4), a G protein-coupled receptor for endogenous medium- or long-chain fatty acids that attenuates metabolic diseases and inflammation, may play a role." (PMID 40085971, 2025). "Finally, based on the experimental success of synthetic Ffar4 agonist to attenuate metabolic disease, we suggest that Ffar4 might be a novel therapeutic target in cardiometabolic disease." (PMID 37075982, 2023). "G-protein Coupled Receptor 120 (GPR120), also known as free fatty acid receptor 4 (FFAR4), which is activated by medium-chain and long-chain fatty acids, has emerged as an interesting potential target for the treatment of metabolic disorders." (PMID 36558150, 2022).
tumor (14 papers, 2017 to 2025). "Pancancer analysis revealed that the FFAR4 were differentially expressed in tumor and paracarcinoma tissues." (PMID 38243188, 2024). "The activation of FFAR4 leading to enhanced glycolysis suggests an increased energy demand in tumor cells." (PMID 38243188, 2024). "FFAR4 was also depicted as a biomarker capable of differentiating tumor stage, with AUC values of 0.933, 0.940, 0.929, and 0.907 for stage I, II, III, and IV LUAD tumors, respectively." (PMID 38243188, 2024). "Evidence suggests that fatty acid receptor FFAR4 plays a tumor-promoting role in adipose tissue-adjacent malignancies, but its clinical relevance remains unexplored." (PMID 30795784, 2019). "Based on that evidence, it is plausible that FFAR4 agonists could play a dual role in tumor and metabolism regulation, thereby holding significant promise in the field of oncology drug development." (PMID 38243188, 2024). "New investigations are needed to determine if both concepts apply in the clinical setting and, in such case, whether the final role of FFAR4 depends on the kind of tumor." (PMID 33113952, 2020). "Moreover, xenograft experiments in nude FFAR4-KO mice demonstrated that the pharmacological stimulation of FFAR4 promotes tumor growth." (PMID 33113952, 2020). "Reduction of CX3CR1 expression leads to reduction in GPR65 and FFAR4 expression, which may affect tumor cell’s ability to uptake FAs, partially explaining reduced omental metastasis." (PMID 29712888, 2018). "Additionally, in silico analysis performed by using Gene Expression Across Normal and Tumor tissue (GENT2) database, revealed FFAR4 significantly downregulated in CRC tissues when compared to healthy controls." (PMID 35013389, 2022). "Notably, all five tumor tissues displayed aberrant FFAR4 expression levels in comparison with their corresponding normal tissues." (PMID 38243188, 2024). "Last but not least, FFAR4 may play different roles in different tumor types." (PMID 38243188, 2024). "Collectively, ω-3 PUFA may confer anti-tumor effects, but these effects are not mediated via FFAR4." (PMID 30795784, 2019).
infection (7 papers, 2020 to 2025). The state of being infected such as from the introduction of a foreign agent such as serum, vaccine, antigenic substance or organism. "The role of FFAR4 in CSE‐induced senescence in HBE cells was investigated through Lv‐FFAR4 infection or TUG891 pharmacological treatment." (PMID 40895192, 2025). "Further investigation on the relationship of FFAR2 and FFAR4 is warranted and may yield a greater understanding of how these two receptors may impact one another, as well as their combined phenotypic alterations to epithelial and immune cells during infection or other diseased states." (PMID 37515117, 2023).
inflammation (3 papers, 2020 to 2025). Aberrant reaction of the microcirculation characterized by movement of fluid and leukocytes from the blood into extravascular tissues. "On the other hand, a synthetic FFAR4 agonist GSK 137647 (administered at the dose of 1 mg/kg BW, i.p., twice daily) alleviated DSS-induced intestinal inflammation in mice, as indicated by significantly reduced MPO activity and macroscopic parameters, such as BW loss." (PMID 34833919, 2021).
FFAR4 also shares sentences with these, for which no sentence is quoted: Glucose intolerance (8 papers); Hyperglycemia (4); inflammatory bowel disease (4); osteoarthritis (4); glucose metabolism disorders (3); melanoma (3); viral infection (3); acute kidney injury (2); adenoma (2); bacterial infection (2); Cerebral ischemia (2); Chronic colitis (2); colorectal adenocarcinoma (2); epilepsy (2); injury (2); schizophrenia (2); abdominal aortic aneurysm (1); adenocarcinoma (1); age (1); alcoholic liver diseases (1); allergic disease (1); Alzheimer disease (1); amyloid (1); Anxiety (1); aortic aneurysm (1); Arrhythmia (1); Arthritis (1); autoimmune (1); autoimmune disease (1); bone metabolic disorders (1).
A further 44 diseases each share a sentence with FFAR4 in 1 paper.